CAV1 (caveolin 1)
Diseases named in the same sentence as CAV1 in open-access papers (continued):
Sharing a sentence is not in itself a finding about the gene and the disease.
tumor (continued). "More importantly, the loss of stromal Cav-1 was associated with metastasis because circulating tumor cells were found in patient blood." (PMID 24949874, 2014). "Endogenous Cav-1 was shown to down-regulate during cell detachment and the level of such a protein was conversely associated with tumor-endothelial adhesion." (PMID 23460862, 2013). "A key hallmark of Lisanti’s “two compartment” theory is a loss of stromal cav-1 and a corresponding up-regulation of cav-1 in tumour cells (i.e. the effects of cav-1 are compartment-specific)." (PMID 23587008, 2013). "Loss of Cav1, in its function as a tumor suppressor and inhibitor of growth factor receptor signalling which stabilizes cell-cell and cell-matrix contacts, is a hallmark of many human cancers including GC." (PMID 23592983, 2013). "The present study aims to explore the clinicopathological significance and prognostic value of both tumor cells and cancer associated fibroblasts (CAFs) Cav-1 in GC." (PMID 23527097, 2013). "Meanwhile in carcinomas of the breast, colon and lung both the loss and gain of Cav-1 have been associated with tumour progression." (PMID 24119769, 2013). "Supporting its role as a tumour suppressor gene, a sporadic dominant negative Cav1 mutation has been described in the literature." (PMID 23521716, 2013). "In cancers, it is increasingly clear that Cav-1 is implicated in regulating multiple cancer-associated processes, ranging from cellular transformation, tumor growth, invasion and metastasis, to multidrug resistance and angiogenesis." (PMID 23527097, 2013). "It has been suggested that loss of Cav-1 in tumor-associated fibroblasts induces aerobic glycolysis in these cells resulting in increased production of pyruvate and lactate." (PMID 22356861, 2012). "This suggests that Cav-1 is expressed at low levels in tumor epithelial cells but at higher levels in regions associated with basal/mesenchymal tumor cells." (PMID 22356861, 2012). "Caveolin-1 is known to promote cell migration, and increased caveolin-1 expression is associated with tumor progression and metastasis." (PMID 22505999, 2012). "On univariate analysis, however, high expression of nuclear Cav-1 was associated with decreased cancer-specific survival (P=0.042), but as only 2% of tumours exhibited high nuclear expression, these results need to be viewed with caution." (PMID 22353809, 2012). "Recently, expression of Caveolin-1 has been reported to be downregulated in CAFs compared to disease-free fibroblasts, and loss of Caveolin-1 in mammary stromal fibroblasts promotes a tumor promoting, CAF-like phenotype." (PMID 21957456, 2011). "In contrast, a higher than average (i.e. > median) CAV1 expression in tumor cell membranes was only linked to male sex (p = 0.03)." (PMID 22152020, 2011). "Alterations of Cav-1 expression in different tumor types are associated with aggressive behavior of cell lines and are proposed to be a prognostic marker for some human malignancies." (PMID 21714887, 2011). "In contrast, a higher than average (i.e. > median or > 3 intensity score) CAV1 expression in tumor cell membranes was only linked to male sex (p = 0.03)." (PMID 22152020, 2011). "A high CAV1 expression in the tumor cell cytoplasm was significantly associated with male sex (p = 0.044), a positive nodal status (p = 0.042), and poor tumor differentiation (p = 0.035)." (PMID 22152020, 2011). "A high CAV1 expression in the tumor cell cytoplasm was significantly associated with male sex (p = 0.04), a positive nodal status (p = 0.04), and poor tumor differentiation (p = 0.04)." (PMID 22152020, 2011). "Association of different patient and tumor specific characteristics with CAV1 protein expression in tumor membranes." (PMID 22152020, 2011). "Similar results were also independently obtained in human prostate cancers,where a loss of stromal Cav-1 was specifically associated with advancedprostate cancer, tumor progression, and metastatic disease." (PMID 20442453, 2010).
tumor (continued). "Yet, how loss of Cav-1 facilitates tumorigenesis and how re-induction of Cav-1 promotes tumor progression remain an open question." (PMID 20700465, 2010). "In fact, the protective effects of Cav-1 against mechanical shearing damage, hypoxia, and nutrient depletion, the stresses that are considered the causes for death of tumor cells during their migration and metastasis, have been reported recently." (PMID 20700465, 2010). "We designed an in-house sandwich ELISA (Exotest) to capture and quantify exosomes in plasma based on expression of housekeeping proteins (CD63 and Rab-5b) and a tumor-associated marker (caveolin-1)." (PMID 19381331, 2009). "In this respect, the recent discovery that caveolin-1 requires presence of E-cadherin in cells to display characteristics associated with its role as a tumour suppressor, is of considerable interest." (PMID 18400052, 2008). "E-cadherin has been shown to be an important permissive element in defining the functions of CAV1, since several characteristics potentially relevant to CAV1 function as a tumor suppressor are compromised in E-cadherin-deficient HT29 cells." (PMID 18694510, 2008). "The analysis revealed significant downregulation of Cav-1 in LNM and that Cav-1 expression was inversely associated with N-stage and positively with tumour differentiation." (PMID 19002186, 2008). "Caveolin-1 constitutes a key switch in tumor development through its association of various signaling molecules." (PMID 19763245, 2008). "The transforming ability of PDK1 in vitro and in vivo is mediated by PKCα and is linked to c-myc function and the expression of caveolin-1, an integral protein component of caveolae known for its role as a tumour suppressor." (PMID 18349831, 2008). "Alternatively, positive caveolin-1-mediated signalling is likely to be more important in those cases where presence of the protein is associated with more aggressive tumour behaviour." (PMID 18400052, 2008). "The potential relevance of these non-conventional pools of caveolin-1 protein is underscored by the fact that secretion of caveolin-1 is associated with enhanced metastatic potential of some tumour cells." (PMID 18400052, 2008). "Both loss and overexpression cav-1 has been described in tumor progression, sometimes within the same tumor type." (PMID 15969750, 2005). "Our data suggest that expression of high cav-1 levels in primary PC tumor cells favor the p42/p44 Erk pathway which is associated with cell growth and survival." (PMID 15969750, 2005). "In all instances, elevated caveolin- 1 levels were associated with tumour progression and poor prognosis." (PMID 14612902, 2003). "Therefore, Cav-1 is associated with an increased risk of early tumor recurrence, metastasis, and reduced overall survival, and is a matrix marker for poor prognosis." (PMID 41030451, 2025). "Moreover, CAV1-deficient mice exhibited increased tumour permeability, angiogenesis, and growth in different tumour models." (PMID 39780187, 2025). "Research indicates that the senescent state of CAFs may correlate with specific markers, such as low expression of Caveolin-1 (CAV1), and is associated with tumor-infiltrating immune cells and PD-L1 levels, suggesting its potential as a prognostic indicator." (PMID 41445734, 2025). "Notably, Cav-1 phosphorylation has been linked to cancer progression, where it enhances tumor cell invasiveness by promoting focal adhesion turnover and cytoskeletal reorganization." (PMID 40243482, 2025). "Notably, CAV-1 modulates signal transduction of multiple tumor-associated pathways, including those mediated by Src family tyrosine kinases and epidermal growth factor receptor (EGFR), which are closely linked to cancer cell proliferation and migration." (PMID 41463331, 2025). "In addition, our study verified that the relative protein level of caveolin-1 from plasma Exos was associated with unfavorable clinical features of PCa and a highly aggressive form of the tumor." (PMID 38542507, 2024).
tumor (continued). "Some results of mass spectrometry analysis showed that in the presence of CAV1, BC cells recruited and secreted sEVs containing cell adhesion-associated proteins, which could significantly promote tumor migration and invasion." (PMID 39494337, 2024). "One might expect that relatively more tumors in METABRIC would have be classified as low CAV1 expressing due to the inverse association between CAV1 expression and tumor aggressiveness." (PMID 38509243, 2024). "Notably, studies on miRNAs in CAV1-deficient tumor matrix cells revealed two key cancer-related miRNAs, MIR31 and MIR34C, which drive mitochondrial autophagy." (PMID 39763653, 2024). "Therefore, the plasma membrane association of Ago2 in tumor cells depends on the Ago2/CAV1 interaction mediated by the CBM of Ago2." (PMID 38649663, 2024). "Indeed, CAV1 has been associated with tumor progression in PCa and the CAV1-induced inhibition of PP1 activity seems to contribute to its tumor promoter role, highlighting the potential of this complex as a drug target." (PMID 39339236, 2024). "A study analyzed 669 tumor specimens with TNBC by immunohistochemistry, showing that lack of stromal CAV-1 expression in TNBC was significantly associated with worse overall survival; conversely, increased mRNA levels of CAV-1 in 141 tumor samples were associated with better overall survival." (PMID 37496657, 2023). "In addition, recent studies have shown that Cav-1 depletion alters mitochondrial morphology in tumor cells, causes disturbed mitochondrial dynamics, and regulates mitophagy, ultimately affecting cancer cell survival." (PMID 37234709, 2023). "High expression of Cav-1 is linked with aggressive tumor phenotypes and metastasis potential." (PMID 36837801, 2023). "This tumor promoting inflammation might be mediated by M2 macrophages that promote tumorigenesis and are linked to CAV1 expression in adipocytes." (PMID 37017811, 2023). "Collectively, COL1A1 down-regulation may inhibit exosome secretion possibly via inhibiting COL I and upregulating CAV-1, thereby inhibiting tumor-associated fibroblast activation and matrix remodeling in the tumor microenvironment." (PMID 38045487, 2023). "CAV-1 colocalizes and interacts with connexin 43, a known tumor suppressor, and it has been speculated that loss of CAV-1 affects the localization of connexin 43 and increases the activation of Ras/AP-1 signaling." (PMID 36532050, 2022). "In parallel, a loss of stromal, particularly fibroblastic CAV1 could be observed, which correlated with tumor progression and therapy resistance, and may therefore be suited as a prognostic marker." (PMID 35155239, 2022). "If so, this could explain the interactions between stromal CAV1 and anthropometric factors or tumor size, where a higher recurrence risk was observed in low-risk patients." (PMID 35660849, 2022). "Thus, targeting fibroblasts and/or limiting fibroblast activation, potentially by limiting the loss of stromal CAV1 seems to be the overarching strategy to inhibit the resistance-promoting signals of the tumor stroma." (PMID 35155239, 2022). "Loss of CAV1 in prostate-tumor stroma is a highly frequent and well-documented perturbation." (PMID 35158857, 2022). "It is now well demonstrated that CAV-1 deficiency in the tumor stroma is positively correlated with distant metastasis, but the mechanism remains unclear." (PMID 36604141, 2022). "The combined increased abundances observed in the proteins encoded by Cav1, Pld3 and Hk3 also highlight the interplay with tumor cell metabolism modifications, leading to the suppression of cancer cell stemness and the deleterious effects of cancer-associated fibroblasts." (PMID 36430209, 2022).
tumor (continued). "Moreover, CAV-1 deficiency in prostate cancer stromal cells can accelerate tumor growth and reduce relapse-free survival of patients by upregulating Akt phosphorylation, resulting in oncogenic gene expression, including transforming growth factor-β1 (TGF-β1)." (PMID 36604141, 2022). "Association of higher Cav1 levels with hypoxic tumor GB indicates its role in tumor hypoxia." (PMID 36121548, 2022). "CAV-1 downregulation in tumor-associated stromal fibroblasts could increase reactive oxygen species (ROS) production, thus inducing oxidative stress followed by autophagy and mitochondrial dysfunction." (PMID 33816265, 2021). "Interestingly, similarly to autophagy, Caveolin-1 has also been implicated both in tumor suppression and progression." (PMID 33718218, 2021). "Increasing CAV1 levels in the penile tumor cells of advanced tumor grades and stages were accompanied by a loss of CAV1 within the tumor stroma, a finding that showed a significant correlation with clinicopathological features of penile SCC, particularly correlating with a reduced overall survival." (PMID 33868995, 2021). "Moreover, they found that the loss of caveolin-1 (Cav-1) in CAFs is associated with tumor progression." (PMID 33391518, 2021). "We went on to explore the risk stratification of patient tumours expressing high levels of Cav-1." (PMID 34490102, 2021). "On the molecular level, the association between glycosphingolipids and Cav-1 mediates the oligomerization of the protein and thus might transduce several membrane-associated functions which might also be relevant for the tumor microenvironment." (PMID 33774714, 2021). "The researchers speculated that Cav-1-deficient CAFs might contribute to tumor growth and angiogenesis by providing energy-rich metabolites (e.g., L-lactate) in a paracrine fashion." (PMID 34373744, 2021). "Furthermore, the loss of caveolin-1 (Cav-1) in CAFs can increase the expression of glycolytic enzymes and promote tumor growth and angiogenesis, which has been proposed as biomarker for the Reverse Warburg effect." (PMID 34852849, 2021). "Meta-analysis of Cav-1 rs7804372 gene polymorphism and tumor susceptibility of digestive system." (PMID 34128850, 2021). "Moreover, Cav-1 appears to be linked to many signalling entities within the GB tumour and as such this work begins to substantiate Cav-1 or its associated signalling partners as candidate target for GB new drug discovery." (PMID 34490102, 2021). "Intriguingly, despite well-established gender differences in the incidence of GB, with males showing the greater incidence, we report here that high Cav-1 tumour expression is associated with a much greater risk to females, approximate 70% reduction in median survival." (PMID 34490102, 2021). "Moreover, Cav-1 appears to be linked to many signalling entities within the GB tumour and as such this work begins to substantiate Cav-1 or its associated signalling partners as candidate target for GB new drug discovery which remains an unmet medical need." (PMID 34490102, 2021). "Significant downregulation of stromal Cav-1 is responsible for the metabolic reprogramming of CAFs, which is characterized by the induction of aerobic glycolysis (also referred to as “reverse Warburg effect”) and autophagy in the tumor-associated stroma." (PMID 32546182, 2020). "In terms of mechanisms, stromal Cav-1 loss could promote tumor progression through various paracrine signaling mechanisms including extracellular matrix remodeling, fibrosis, and modulation of the tumor microenvironment." (PMID 32528105, 2020).
tumor (continued). "In addition, there are several reports which explain the possible reasons why the loss of CAV1 in tumor stroma is considered a poor prognostic marker in cancer from a metabolic point of view." (PMID 32458269, 2020). "There is increasing attention to a specific role of Cav-1 in the tumor-associated stroma." (PMID 32633727, 2020). "Furthermore, there was a trend toward a less intense staining for ceramide and ASMase in CAV1-deficient stromal compartments of tumor samples with higher Gleason grade." (PMID 32273493, 2020). "In detail, CAFs produced energy metabolites to create the necessary energy-rich microenvironment for facilitating tumor growth through higher aerobic glycolysis (reverse Warburg effect) and autophagy, which was associated with the loss of stromal caveolin-1 (Cav-1) expression." (PMID 32050640, 2020). "Interestingly, during tumor progression, the switching of cadherins at the plasma membrane is associated with augmented CAV1 expression." (PMID 32458269, 2020). "The role for caveolins as guardians against oncogenic transformation is supported by reports that loss of Cav-1 in tumor-associated fibroblasts drives a change in phenotype from “normal” to “fuel-supplier,” modifying the stromal environment of cancer cells into a medium favoring survival." (PMID 33195223, 2020). "These preliminary results suggest that loss of shorter transcripts of CAV1 is associated with tumor transformation into a more aggressive state and that these two different isoforms could exert opposite effects on tumor progression." (PMID 32825330, 2020). "Loss of Cav-1 in the tumor stroma activates TGF-β signaling in CAFs." (PMID 32546182, 2020). "Cav-1 has been reported to play an important role in the progression of carcinoma as well as involved in multiple cancer-associated processes such as tumor growth, cell migration/metastasis, cell death and survival, multidrug resistance (MDR), and angiogenesis." (PMID 31581454, 2019). "Increased FAK stability, migration, and invasion attributed to CAV1 presence involves the Src/Rho/Rho-associated kinase (ROCK) signaling axis and CAV1 phosphorylation on Y14 functions as an effector of Rho/ROCK signaling promoting tumor progression and metastasis." (PMID 31362353, 2019). "Cav1 phosphorylation by Src kinase on tyrosine 14 is closely associated with focal adhesion dynamics and tumor cell migration, however the role of pCav1 in vivo in tumor progression remains poorly characterized." (PMID 31803361, 2019). "In stromal cells, loss of CAV1 expression promotes mitochondrial metabolism, thereby increasing oxidative stress, genomic instability and cell transformation, which is consistent with the notion that CAV1 functions as a tumour suppressor." (PMID 30209302, 2019). "In addition, the over-expression of cav-1 has been associated with tumour suppression, while ER-α and Her-2/neu are tumour promoters." (PMID 31619022, 2019). "Oxidative stress related loss of stromal caveolin-1 (Cav-1) increases the production of ROSs in tumor cells, which initiates the cascade of oxidative stress in CAFs via a positive feedback mechanism and plays a role in cancer proliferation, recurrence and prognosis." (PMID 31803621, 2019). "Moreover, loss of stromal CAV1 in a tumor model was proposed as a marker of inflammation and a predictor of poor outcome." (PMID 30246033, 2018). "In addition, the high expression level of caveolin-1 was associated with venous infiltration and tumor metastasis, indicating that high caveolin-1 expression promoted the occurrence, progression, infiltration, and metastasis of tumors." (PMID 30424755, 2018). "We hypothesized that CAV1 loss could also be involved in inflammation, which is a common feature of many pathologies, from cardiovascular diseases to tumor development." (PMID 30246033, 2018).